CXCR4 (C-X-C motif chemokine receptor 4)
Diseases named in the same sentence as CXCR4 in open-access papers (continued):
Sharing a sentence is not in itself a finding about the gene and the disease.
colitis (19 papers, 2011 to 2025). Inflammation of the colon. "Collectively, these findings indicated that overexpression of CXCR4 promoted colitis-associated tumorigenesis and progression via recruiting macrophages and MDSCs from the circulatory system to inflamed colonic mucosa." (PMID 30678736, 2019). "The results implied that overexpression of CXCR4 exacerbated colitis-associated tumorigenesis in Apcmin/+ mice." (PMID 30678736, 2019). "We found that high CXCR4 expression exacerbated colitis-associated cancer in villin-CXCR4 transgenic mice." (PMID 30678736, 2019). "DSS-induced body weight loss in CXCR4+/− mice was more obvious than in WT mice, whereas CXCR4 antagonist AMD3100 attenuated body weight loss during colitis." (PMID 30678736, 2019). "In similar, CXCR-4 gene overexpressed BMSCs (CXCR-BMSCs) exerted increased homing of BMSCs into the colon in the colitis murine model." (PMID 40472038, 2025). "Other studies showed that blocking CXCR4 attenuates colonic damage in the murine colitis model, indicating its critical role in the intestinal inflammatory response and CRC progression." (PMID 35615089, 2022). "According to previous studies, blockade of the CXCL12/CXCR4 axis by the specific antagonist AMD3100 attenuates experimental colitis in a murine model by inhibiting chronic inflammation and enhancing epithelial barrier integrity." (PMID 35363937, 2022). "Blocking the CXCL12/CXCR4 axis ameliorates experimental colitis in a murine model, indicating a crucial role in the intestinal inflammatory response." (PMID 35363937, 2022). "Villin promoter-dependent overexpression of the transgene CXCR4 and CXCR7 increased colitis and tumorigenesis compared to over expression of CXCR4 or CXCR7 alone in mouse models." (PMID 34298991, 2021). "In this study, we clearly demonstrated that LA effectively promotes expression of the CXCR4 gene of BMMSCs, thereby promoting the migration of BMMSCs, and it reduced colitis inflammation in mice after injecting LA-pretreated rBMMSCs." (PMID 34804422, 2021). "AMD3100, CXCR4 antagonist, exerts therapeutic effects on experimental colitis by inhibiting colonic inflammation and enhancing epithelial barrier integrity." (PMID 34531745, 2021). "CXCR4+ T cells in mice with established TNBS-induced colitis were enriched among CD81+ T cells by 2.6- or 3.9-fold versus CD81− T cells with or without SEB stimulation, respectively." (PMID 32332834, 2020). "In this study, we demonstrate that the chemotactic interaction of SDF-1/CXCR4 system promotes homing of ERCs to the impaired colon tissue in the DSS-induced colitis model in mice." (PMID 31286993, 2019). "To confirm the effects of CXCR4 high-expressing ERCs in vivo, we have analyzed the expression of splenic immune cell populations by flow cytometry on day 10 after colitis induction." (PMID 31286993, 2019). "The aim of the present study was to investigate the role of SDF-1/CXCR4 axis in the immunomodulation of ERCs on the experimental colitis." (PMID 31286993, 2019). "Pretreatment with cytokines has led to some success in this area; for example, treatment with IFN-γ leads to increased CXCR4 expression and migration of MSCs towards the site of damage in mouse model of colitis." (PMID 28705238, 2017). "Present study identified the therapeutic effect of CXCR4 antagonist AMD3100 on experimental colitis." (PMID 22073304, 2011). "The immunostaining of claudin-5 was decreased in intensity in colitis mice, and enhanced when treated with CXCR4 antagonist AMD3100." (PMID 22073304, 2011). "The immunostaining of claudin-1 was decreased in intensity in colitis mice, and enhanced when treated with CXCR4 antagonist AMD3100." (PMID 22073304, 2011). "Block of CXCR4 significantly ameliorates murine experimental colitis, indicating a possible role of this CXCR4 in intestinal inflammatory response." (PMID 22073304, 2011).
colitis (continued). "A CXCR4 antagonist effectively reduces colonic inflammation in the DSS colitis model and the IL-10 knockout mouse model, suggesting it may be a promising therapeutic intervention." (PMID 39070795, 2024). "In addition, SDF-1 effectively enhances the expression of CXCR4 on the surface of ERCs and thereby markedly improves the therapeutic effect of ERCs in alleviating colitis." (PMID 31286993, 2019). "Our results may suggest that an SDF-1-induced high level of CXCR4 expression enhances the immunomodulation of ERCs in alleviating experimental colitis in mice." (PMID 31286993, 2019). "Indeed, inhibition of CXCR4 was found to exert anti-inflammatory effects in experimental models of joint inflammation, colitis and allergic lung inflammation." (PMID 24695674, 2014). "In present study, we demonstrated marked mucosal damage and inflammatory responses in DSS-induced colitis, and that could be ameliorated by CXCR4 antagonist AMD3100." (PMID 22073304, 2011). "Hence, the aim of this study was to determine whether the therapeutic effect of ERCs on the experimental colitis could be determined by the SDF-1/CXCR4 axis via pretreatment of ERCs with SDF-1." (PMID 31286993, 2019). "Using a murine model of dextran sulfate sodium (DSS)-induced colitis, the study further demonstrates that CXCR4 expression is elevated on leukocytes and that CXCL12 expression increases in colonic tissue when colitis is induced." (PMID 39070795, 2024). "LA pretreatment of MSCs can improve the migration ability of MSCs by increasing the expression of CXCR4, thereby improving the therapeutic effect of DSS-induced colitis mice." (PMID 34804422, 2021). "The anti-CD81 antibody inhibited the migration of splenocytes from mice with TNBS-induced colitis, which was induced by SDF-1, one of the ligands for chemokine receptor CXCR4 and a chemokine involved in the pathogenesis of IBD 1,8." (PMID 32332834, 2020). "Furthermore, overexpression of CXCR4 was found to promote the epithelial-mesenchymal transition (EMT) and infiltration of myeloid-derived suppressor cells (MDSCs) and macrophages in colonic tissue, accelerating colitis-associated and Apc mutation-driven colorectal tumorigenesis and progression." (PMID 30678736, 2019). "In the present study, the experimental colitis was induced by administration of 5% DSS for 7 days, and CXCR4 antagonist AMD3100 was administered intraperitoneally once daily during the study period." (PMID 22073304, 2011). "In the present study, we firstly assessed the effects of CXCR4 antagonist AMD3100 on cytokines, intestinal barrier, and colonic claudins expression in DSS-induced colitis in mice." (PMID 22073304, 2011). "To date, targeting of chemokine receptors such as CCR2, CCR5, CCR6, CXCR3, CXCR4 and CX3CR1 by gene disruption or antagonistic peptides has been found to protect animals from DSS colitis." (PMID 21283540, 2011). "Treated with CXCR4 antagonist AMD3100 significantly promoted colonic claudin-1, claudin-3, claudin-5, claudin-7 and claudin-8 expressions, and also decreased colonic claudin-2 in colitis mice." (PMID 22073304, 2011). "Previous studies demonstrated that CXC chemokine receptor 4 (CXCR4) antagonists could reduce colonic inflammation and mucosal damage in dextran sulfate sodium (DSS)-induced colitis." (PMID 22073304, 2011). "In conclusion, the present study demonstrated that CXCR4 antagonist AMD3100 modulated the expression of colonic claudins, enhanced intestinal barrier function, also attenuated colonic inflammation in DSS-induced colitis." (PMID 22073304, 2011). "Moreover, in the present study, we found that treated with CXCR4 antagonist AMD3100 significantly promoted colonic claudin-1, claudin-3, claudin-5, claudin-7 and claudin-8 expressions, and also decreased colonic claudin-2 in colitis mice." (PMID 22073304, 2011). "Although the expression level of CXCR4 did not change, almost all macrophages became highly positive for CCR2 with the development of colitis." (PMID 31189971, 2019).
colitis (continued). "The CXCR4 expression did not change, however, CX3CR1− fibrocytes gradually increased with the development of colitis." (PMID 31189971, 2019).
coronary artery disease (19 papers, 2012 to 2025). "Specifically, reduced exercise-induced mobilisation of CD34+CXCR4+ HPCs is associated with increased CVD in patients with coronary artery disease." (PMID 35222269, 2022). "A recent report found that BM CXCR4+ cells are associated with functional improvements over time in patients with ischemic heart disease." (PMID 30929097, 2019). "This impairment leads to reduced neovascularization, highlighting the potential of targeting CXCR4 to improve outcomes in coronary artery disease." (PMID 38786076, 2024). "Recent evidence indicates that chemokine receptor CXCR4 signaling in endothelial progenitor cells is impaired in individuals with coronary artery disease." (PMID 38786076, 2024). "Recently, administration of Cxcl12 to injured hearts, a chemokine that binds the receptor Cxcr4 and is key for EC chemotactic migration, has shown a significant effect on the development of collateral arteries in ischemic heart disease." (PMID 33078209, 2021). "A study in coronary artery disease patients showed that the dysregulation of CXCR4 signaling reduced the migratory capacity of EPCs in these patients compared to healthy subjects." (PMID 30324106, 2018). "Furthermore, the SDF-1/CXCR4 axis has emerged as a promising therapeutic target for ischemic heart disease." (PMID 38786076, 2024). "We hypothesize that these compounds can modify CXCL12/CXCR4/CXCR7 pathway offering benefits for coronary artery disease patients." (PMID 35120520, 2022). "In a recent paper, Doring and collaborators demonstrated that CXCR4, the receptor of CXCL12 (whose expression and plasma levels were previously associated with coronary artery disease), was able to confer cell-specific athero-protective effects preserving endothelial function in mice." (PMID 32748835, 2020). "In cardiac disorders, CXCR7, CXCR4 and CXCL12 expression in platelets affects the disease severity of coronary artery disease." (PMID 32098047, 2020). "Tan IIA has been shown to increase CXCL12 expression at the site of injury as well as CXCR4 on transplanted MSCs, leading to enhanced MSC migration to the injured area, which may prove effective in the treatment of ischemic heart disease." (PMID 32582713, 2020).
Ewing sarcoma (19 papers, 2011 to 2024). A small round cell tumor that lacks morphologic, immunohistochemical, and electron microscopic evidence of neuroectodermal differentiation. "An illustrative instance of this phenomenon is the documented reciprocal influence between CXCR4 and PDGF signaling in Ewing sarcoma, wherein heightened CXCR4 expression is associated with metastasis and unfavorable patient prognosis." (PMID 39154307, 2024). "Among GPCRs, the chemokine receptor CXCR4 has been linked to metastasis formation in many cancers, including Ewing sarcoma." (PMID 32326412, 2020). "Exploring potential molecular mechanisms underlying this effect, we found that Ewing sarcoma cell lines divided into classes of high- and low-level CXCR4 surface expression." (PMID 29776413, 2018). "Because such CXCR4 splicing variants have been reported in Ewing sarcoma, we first examined CXCR4 protein expression in Western blots of whole cell lysates." (PMID 29776413, 2018). "CXCR4 expression has been associated with metastasis and tumor progression in various tumor types, including Ewing sarcoma (EWS)." (PMID 28549419, 2017). "Thus, elucidation of the mechanisms underlying CXCR4 regulation in Ewing sarcoma could provide insights into the molecular mechanisms of Ewing sarcoma cell heterogeneity and tumor progression." (PMID 27528222, 2016). "Accordingly, targeting the CXCL12/CXCR4 axis inhibited the metastatic capability of Ewing sarcoma cells." (PMID 34440844, 2021). "In Ewing sarcoma, the expression of CXCR4 is highly dynamic as it is transiently induced by microenvironmental stress such as hypoxia or serum-deprivation." (PMID 34440844, 2021). "Despite their heterogeneous findings, our previous and current studies together endorse a role for CXCR4 signaling in Ewing sarcoma proliferation in vitro." (PMID 29776413, 2018). "One central limitation to our study is that we did not yet investigate how plerixafor elicits pro-proliferative and migratory responses in CXCR4-low Ewing sarcoma cell lines." (PMID 29776413, 2018). "The platelet-derived growth factor receptor beta (PDGFRB) has been shown to contribute to Ewing sarcoma growth and metastasis in vitro and in vivo and demonstrated the most prominent activation upon plerixafor treatment in A673 CXCR4-low cells." (PMID 29776413, 2018). "Plerixafor treatment of Ewing sarcoma cell lines led to changes in RTK phosphorylation patterns in both CXCR4-high and -low lines." (PMID 29776413, 2018). "In parallel, additional RTKs affected by plerixafor point to a broader signaling interconnection between CXCR4 and receptor tyrosine kinases in Ewing sarcoma." (PMID 29776413, 2018). "Recent gene expression analyses revealed a correlation between Ewing sarcoma CXCR4 expression and metastatic phenotype and shortened patient survival." (PMID 29776413, 2018). "PDGFRB was identified as a candidate driver RTK and potential therapeutic co-target for CXCR4 in Ewing sarcoma." (PMID 29776413, 2018). "To investigate plerixafor (AMD3100) as an inhibitor of proliferative CXCR4 signaling in Ewing sarcoma, we performed in vitro cell proliferation and viability assays in several Ewing sarcoma cell lines including the low-passage cell culture DC-ES-6." (PMID 29776413, 2018). "A band of ~ 45 kDa corresponded to the glycosylated CXCR4 monomer and was present in all cell lines including HL-60, whereas a 55 kDa isoform was restricted to Ewing sarcoma lines and thus dispensable for the proliferative plerixafor-response of HL-60 cells." (PMID 29776413, 2018). "Nevertheless, both studies indicated potential for plerixafor to disrupt respective pro-tumorigenic CXCR4 actions in Ewing sarcoma." (PMID 29776413, 2018). "Earlier studies on CXCR4 protein expression in Ewing sarcoma yielded contradictory results when compared to CXCR4 RNA expression studies." (PMID 28549419, 2017).
Ewing sarcoma (continued). "From a mechanistic perspective, we found that phenotypic heterogeneity of CXCR4 in Ewing sarcoma tumor cells is, in part, epigenetically mediated." (PMID 27528222, 2016). "We recently showed that expression of CXCR4 is heterogeneous and dynamically regulated in Ewing sarcoma, an aggressive bone and soft tissue tumor that peaks in adolescents and young adults." (PMID 27528222, 2016). "In Ewing sarcoma cell lines we have shown that CXCR4 expression is normally expressed by only a minority of cells under ambient conditions." (PMID 27528222, 2016). "In Ewing sarcoma samples, H3K4me3 was detected at the CXCR4 promoter in chromatin that had been isolated by the H3K27me3-directed antibody (K27/K4) and vice versa (K4/K27)." (PMID 27528222, 2016). "We recently reported that the chemokine receptor CXCR4 is induced in Ewing sarcoma cells in response to microenvironmental stress." (PMID 27528222, 2016). "A previous study showed that the dynamic change of the expression level of CXCR4 in Ewing sarcoma cells depends on the change of cellular stresses, such as growth factor deprivation, hypoxia, and space constraints." (PMID 26083776, 2015). "Taking into account that IGF2BP3 sustains IGF1R expression as well, we can speculate that co-targeting the IGF axis and CXCR4 in Ewing sarcoma cells expressing high levels of IGF2BP3 might represent a valuable therapeutic option." (PMID 34440844, 2021). "Notably, the subpopulation of Ewing sarcoma cells characterized by high CXCR4 expression display high migratory capabilities." (PMID 34440844, 2021). "Further, still unknown mechanisms that mediate spheroidal adhesion under simulated microgravity in Ewing’s sarcoma, independent from CXCR4, can therefore be postulated." (PMID 31810195, 2019). "Given this initial evidence for CXCR4 as a molecular target, matched with plerixafor as a targeted agent that reached clinical application in children, we aimed to investigate the anti-tumor activities of plerixafor in Ewing sarcoma." (PMID 29776413, 2018). "Therefore, we studied the membranous CXCR4 expression in Ewing sarcoma cell lines using MSAP-Ac-TZ14011." (PMID 28549419, 2017). "The fluorescently tagged CXCR4 targeting peptide could enable in vivo detection of CXCR4 expression in Ewing sarcoma which may help to stratify cases for anti-CXCR4 therapy." (PMID 28549419, 2017). "In addition, we evaluated the chromatin state of the CXCR4 locus in a panel of Ewing sarcoma cell lines to determine if epigenetic plasticity contributes to stress-dependent activation of CXCR4." (PMID 27528222, 2016). "Thus, repression of CXCR4 expression in Ewing sarcoma is, at least in part, dependent on EZH2 and on the presence of the H3K27me3 modification at the gene promoter." (PMID 27528222, 2016). "In addition, there is evidence that local growth of Ewing sarcomas is also promoted by CXCR4 pathway activation." (PMID 27528222, 2016). "Thus, CXCR4 positive tumor cells are likely to play a fundamental role in local progression of Ewing sarcoma." (PMID 27528222, 2016). "In the current study we assessed plasticity of CXCR4 in Ewing sarcoma tumor cells in vivo." (PMID 27528222, 2016). "This upregulation of CXCR4 was associated with phenotypic transition of Ewing sarcoma cells from relatively non-motile states to cells that actively migrated and invaded towards the CXCL12 ligand." (PMID 27528222, 2016). "To evaluate the chromatin state of the CXCR4 promoter in Ewing sarcoma we performed ChIP-PCR studies using antibodies directed against the H3K4me3 and H3K27me3 histone modifications and genomic PCR primers specific for the CXCR4 promoter." (PMID 27528222, 2016). "Previously, expression of CXCR4 transcript was found to be increased in tumor biopsies from patients with metastatic Ewing sarcoma compared to localized tumors, suggesting that CXCR4 signaling may contribute to tumor metastasis." (PMID 27528222, 2016).